KLK11 (kallikrein related peptidase 11)
Diseases named in the same sentence as KLK11 in open-access papers (continued):
Sharing a sentence is not in itself a finding about the gene and the disease.
cardiac hypertrophy (1 paper, 2021). "In the present work, we aimed to investigate the potential functions of KLK11 in cardiac hypertrophy and the underlying mechanisms." (PMID 34059001, 2021). "We also induced cardiac hypertrophy in mice and observed the upregulation of KLK11 in hypertrophic hearts." (PMID 34059001, 2021). "Using human hypertrophic heart tissues, we demonstrated the overexpression of KLK11 in cardiac hypertrophy." (PMID 34059001, 2021). "In the present work, we demonstrated that KLK11 promoted the development of cardiac hypertrophy via activating AKT-mTOR signaling and protein synthesis." (PMID 34059001, 2021). "In the mouse model of cardiac hypertrophy, we also observed the overexpression of KLK11." (PMID 34059001, 2021). "Next, we induced cardiac hypertrophy with TAC surgery in mice to test the expression of KLK11." (PMID 34059001, 2021). "However, the roles of KLK11 in cardiovascular diseases, such as cardiac hypertrophy, remain to be explored." (PMID 34059001, 2021). "Here we investigated the roles of Kallikrein 11 (KLK11) in cardiac hypertrophy." (PMID 34059001, 2021). "To test whether KLK11 also regulates cardiac hypertrophy in vivo, we silenced KLK11 in mouse hearts with AAV9-mediated shRNA." (PMID 34059001, 2021). "In this study, we aimed to investigate the roles of KLK11 in cardiac hypertrophy." (PMID 34059001, 2021). "Collectively, these findings demonstrated that KLK11 was overexpressed in hypertrophic hearts of humans and mice, implicating that KLK11 may be involved in cardiac hypertrophy." (PMID 34059001, 2021). "In this work, we identified KLK11 as a regulator of cardiac hypertrophy." (PMID 34059001, 2021). "To test whether KLK11 promoted cardiac hypertrophy, we used an in vitro cardiomyocyte hypertrophy model." (PMID 34059001, 2021). "Collectively, these findings demonstrated that KLK11 promoted AKT-mTOR signaling to activate protein synthesis and promote cardiac hypertrophy." (PMID 34059001, 2021). "Besides, we knocked down KLK11 in mouse hearts and observed that KLK11 loss suppressed TAC-induced decrease in heart function (fraction shortening and ejection fraction) and increase in heart weight, cardiomyocyte size, as well as overexpression of fetal genes associated with cardiac hypertrophy." (PMID 34059001, 2021). "Therefore, KLK11 may serve as a target for the treatment of cardiac hypertrophy." (PMID 34059001, 2021).
colorectal adenocarcinoma (1 paper, 2021). The most common type of colorectal carcinoma. "For instance, KLK11 mRNA expression predicts poor disease-free and overall survival in patients with colorectal adenocarcinoma." (PMID 34059001, 2021).
cutaneous melanoma (1 paper, 2017). A primary melanoma arising from atypical melanocytes in the skin. "In concordance with our findings, a previous gene expression study revealed that KLK7, KLK4, and KLK11 expression is correlated with metastatic dissemination and associated with overall survival of patients with primary cutaneous melanoma." (PMID 28636767, 2017).
Hyperkeratosis (1 paper, 2025). Hyperkeratosis is a histopathological term defining a thickened stratum corneum and may be present in many different skin conditions, with many possible overlaps. "Apart from the roles of KLK11 in prostate, a presumably pathogenic variant of the KLK11 gene appears to be one cause of Mendelian disorders of cornification (MeDoC), which is a group of heterogeneous skin conditions of hyperkeratosis and dysregulated scaling." (PMID 41516101, 2025).
lung carcinoma (1 paper, 2014). "In the present study, serum KLK11 levels were significantly elevated in patients with lung cancer compared with control subjects, making them potential adjunctive tools for diagnosis of lung cancer." (PMID 24510347, 2014). "Kaplan–Meier survival curves further demonstrate that lung cancer patients with high KLK11 have substantially longer PFS and OS (P < 0.05), compared to those with low KLK11 cancer." (PMID 24510347, 2014). "Among these enzymes are many members of human tissue kallikrein family of secreted serine proteases, including KLK11, a promising biomarker for lung cancer diagnosis, and prognosis." (PMID 24510347, 2014). "Furthermore, at a cutoff point of 1.05 ng/ml, KLK11 had a sensitivity of 91.3 % and a specificity of 72.5 % for the prediction of lung cancer." (PMID 24510347, 2014).
melanoma (1 paper, 2013). A malignant, usually aggressive tumor composed of atypical, neoplastic melanocytes. "Compared to melanomas without ulceration, ulcerated melanomas were characterised by downregulation of members of the kallikrein serine protease family (i.e., KLK7, KLK5, KLK11), which are related to angiogenesis and the degradation of extracellular matrix components." (PMID 23383013, 2013).
ovarian tumor (1 paper, 2017). "KLK11 expression was also significantly higher in ovarian tumor samples than in normal samples." (PMID 29095848, 2017).
pancreatic cancer (1 paper, 2021). "KLK6, KLK7, KLK8, KLK10 and KLK11 were coexpressed and upregulated in tissues from pancreatic cancer patients compared to normal pancreas." (PMID 34439122, 2021).
papillary thyroid cancer (1 paper, 2025). "Earlier studies have indicated that KLK7, KLK10, and KLK11 are linked to the survival rates and immune reactions of individuals with papillary thyroid cancer (PTC)." (PMID 39991575, 2025).
Renal clear cell carcinoma (1 paper, 2018). "Renal clear cell carcinoma had six KLKs in which increased expression was associated with overall survival (KLK2: HR = 1.69; KLK4: HR = 1.63; KLK8: HR = 1.71; KLK10: HR = 2.12; KLK11: HR = 1.76; and KLK14: HR = 1.86)." (PMID 29707153, 2018).
Sjögren syndrome (1 paper, 2021). "For example, elevated immunoglobulin to tissue KLK11 was observed in patients with Sjögren syndrome." (PMID 34059001, 2021). "Although the roles of KLK11 have been identified in cancer biology and Sjögren syndrome, the roles of KLK11 in cardiovascular diseases are largely unknown." (PMID 34059001, 2021).
tumor (20 papers, 2014 to 2025). "First, the relative expression levels of KLK10 and KLK11 mRNA were analyzed with respect to their association with established clinical variables, including age, lymph node status, and tumor size." (PMID 36294951, 2022). "The findings of this study help to expand the database of KLK11 and tumor associations." (PMID 38022651, 2023). "KLK5 may also affect the extracellular proteolytic network in the tumor cell microenvironment by activating the zymogen forms of other tumor-associated proteases including pro-urokinase-type plasminogen activator (pro-uPA) and pro-KLK11." (PMID 31307411, 2019). "All in all, both KLK10 and KLK11 appear to exhibit tumor-promoting properties in some cancer entities." (PMID 36294951, 2022). "Then, using GEPIA bioinformatics analysis, KLK11 mRNA was significantly overexpressed in CCA tumor tissues compared with normal tissues (p < 0.05)." (PMID 34067437, 2021). "Among the tumor biological factors (added separately to the base model), KLK11 mRNA levels significantly contribute to the base model for OS (HR = 0.40, 95% CI = 0.20–0.78, p = 0.007) and PFS (HR = 0.47, 95% CI = 0.26–0.86, p = 0.015)." (PMID 29095848, 2017). "In multivariable Cox analysis, KLK11 mRNA expression levels, apart from residual tumor mass, remained an independent predictive marker for OS (p = 0.007) and PFS (p = 0.015)." (PMID 29095848, 2017). "The levels of KLK11 were significantly correlated with tumor-node-metastasis (TNM) stage (P = 0.000), lymph node metastases (P = 0.000), and distant metastases (P = 0.000)." (PMID 24510347, 2014). "Although the preceding research established that KLK11 is associated with tumor diagnosis and prognosis, no studies have reported a link between KLK11 and HCC." (PMID 38022651, 2023). "Furthermore, KLK11 plays a role in tumor progression and metastasis via the insulin-like growth factor (IGF) signaling pathway." (PMID 34067437, 2021). "The evaluation of the relationship between KLK11 expression and patients with different nuclear grades by using the Kruskal-Wallis statistical test indicated that the average KLK11 with tumor grade was statistically significant (p = 0.017), and in grade I, it was higher than grade II and III." (PMID 31983196, 2020). "Also, the mean KLK11 had a statistically significant reverse correlation with tumor grade (p = 0.017)." (PMID 31983196, 2020). "Since C1QBP and KNG1 are supposed to be involved in the crosstalk between KLK11 and CCDC25, their role in tumor metastasis should be explored." (PMID 34067437, 2021). "The tumor biological role of KLK11 is not clear at all, since numerous studies have reported a contradictory prognostic impact of KLK11 even in the same type of cancer." (PMID 29095848, 2017). "However, the limited expression of both KLK10 and KLK11 in healthy tissue, together with the overall negative impact on tumor progression make both KLKs interesting therapeutic targets, in addition to their biomarker potential." (PMID 36294951, 2022). "Thus, by this method, we are not able to dissect whether high KLK11/KLK15 tumor or stromal cell-mRNA expression or both is relevant for the better prognosis of the patients." (PMID 29095848, 2017).
cancer (18 papers, 2004 to 2024). A tumor composed of atypical neoplastic, often pleomorphic cells that invade other tissues. "The pathophysiological mechanisms driving the tumorigenic properties of KLK10 and KLK11 have been addressed in several studies on various cancer types." (PMID 36294951, 2022). "Accumulating evidence showed that KLK11 critically participated in the development and drug resistance of human cancer." (PMID 34059001, 2021). "Although some studies have identified the roles of KLF11 in cancer biology, the functions of KLK11 in other metabolism-related diseases are still covered." (PMID 34059001, 2021). "Whereas some studies point to an association of elevated KLK11 levels with an unfavorable prognosis in ovarian, gastric, and lung cancer, others report of a link between low KLK11 levels with poor outcome, again in ovarian, gastric, and lung tumors." (PMID 29095848, 2017). "Cytoband location 19q13.3–q13.4 was common for differentially expressed KLK gene family (KLK12, KLK11, KLK10, and KLK13), the serine proteases encoded from this Kallikrein gene family have been implicated in various cancers." (PMID 25505737, 2014). "It is worth mentioning, however, that the only cancer library where KLK11 was detected was described in the database as ‘Low grade malignancy, with some in situ component’." (PMID 14710225, 2004). "KLK11 has significant roles in physiological and pathological processes, including cancer biology." (PMID 34059001, 2021). "Thus, the overall role of KLK11 in the progress of cancer remains inconsistent." (PMID 36294951, 2022). "In addition to cancer biology, KLK11 also participated in other pathological processes." (PMID 34059001, 2021). "Using the KLK-CANMAP, a tool that includes several other cancer datasets, we again found the KLK6, KLK7, KLK8 and KLK10 cluster, with the exception of KLK11, which was upregulated in PDAC compared to normal pancreas tissues." (PMID 34439122, 2021). "On the other hand, the impact of KLK11 mRNA levels as biomarker can be considered only in the context of the subgroup / type of cancer, in which the clinical relevance of this marker has been proven, because in other cancer (sub-)types the situation could be very different." (PMID 29095848, 2017). "KLK11 was significantly overexpressed in circulating L-EVs of Thy3f cancer compared with non-cancer patients." (PMID 39787026, 2024). "With respect to the cancer group, the upregulation of mir-195-3p, KLK11, A1AG2, SMIM1, and the downregulation of mir-3176, mir-205-5p, novel-hsa-mir-208-3p, mir-3529-3p and let-7i-3p, CXCL7, TBB1, ACTN1 and BIP were identified compared with the non-cancer group." (PMID 39787026, 2024). "Slightly higher expression levels were detected for KLK11 and KLK12 in normal breast compared to cancer, although not statistically conclusive." (PMID 14710225, 2004).
inflammation (1 paper, 2018). Aberrant reaction of the microcirculation characterized by movement of fluid and leukocytes from the blood into extravascular tissues. "Overexpression of Klk11 can promote the occurrence of lung inflammation in rats." (PMID 30245729, 2018).
KLK11 also shares sentences with these, for which no sentence is quoted: Hyperglycemia (3 papers); cardiovascular diseases (2); Obesity (2); allergic conjunctivitis (1); atherosclerosis (1); autoimmune disease (1); benign tumors (1); bronchiectasis (1); colon adenocarcinoma (1); diabetes (1); epithelioid mesotheliomas (1); head-neck squamous cell carcinoma (1); Hepatic steatosis (1); hepatocellular carcinoma (1); Hyperinsulinemia (1); hyperlipidemia (1); hypertrophy (1); infection (1); Insulin resistance (1); lung squamous cell carcinoma (1); metabolic disorders (1); metabolic syndrome (1); metastatic colorectal cancer (1); metastatic disease (1); neuroendocrine carcinoma (1); non-small cell lung carcinoma (1); oral cancer (1); papillary renal cell carcinoma (1); prostate disease (1); prostate tumors (1).
A further 4 diseases each share a sentence with KLK11 in 1 paper.